SMAP1 (small ArfGAP 1)
Description:
GTPase activating protein that acts on ARF6. Plays a role in clathrin-dependent endocytosis. May play a role in erythropoiesis (By similarity).
Synonyms: FLJ13159; SMAP-1
Tractability: Antibody: UniProt places it where antibodies can reach, with medium confidence; its Gene Ontology location is reachable by antibodies, with medium confidence; the Human Protein Atlas places it where antibodies can reach. PROTAC: ubiquitination databases record sites on it; its protein half-life has been measured.
Gene: Protein-coding gene on chromosome 6 (70,667,776 to 70,862,015, forward strand). Ensembl gene ENSG00000112305.
Subcellular location: Cell membrane
Subcellular location (Human Protein Atlas): Cytosol; Plasma membrane; Golgi apparatus
Gene Ontology:
Molecular function: GTPase activator activity; clathrin binding; metal ion binding
Biological process: regulation of clathrin-dependent endocytosis
Cellular component: cytoplasm; plasma membrane
Genetic constraint (gnomAD): Loss-of-function variants: 12 observed, 39.57 expected, observed/expected ratio (o/e) 0.3, 90% interval 0.19 to 0.49. The upper end of that interval is the gene's LOEUF score, 0.49, which puts it in group 2 of 6, group 1 being the genes least tolerant of losing a copy. Missense variants: 490 observed, 485.13 expected, observed/expected ratio (o/e) 1.01, 90% interval 0.94 to 1.09. Synonymous variants: 187 observed, 174.34 expected, observed/expected ratio (o/e) 1.07, 90% interval 0.95 to 1.21.
Homologues: Orthologues: chimpanzee SMAP1 (98% identical), dog SMAP1 (95% identical), rat Smap1 (92% identical), macaque SDHAF4 (92% identical), pig SMAP1 (91% identical), rabbit SMAP1 (89% identical), mouse Smap1 (87% identical), guinea pig SMAP1 (77% identical), tropical clawed frog smap1 (70% identical), zebrafish smap1 (60% identical). Paralogues in human: SMAP2 (45% identical), ARAP1 (21% identical), ADAP1 (20% identical), ARAP2 (20% identical), ADAP2 (19% identical), AGFG1 (19% identical), ARAP3 (18% identical), ASAP2 (16% identical), AGFG2 (16% identical), ASAP1 (16% identical), ASAP3 (15% identical), ACAP2 (15% identical), and 16 more.
Diseases named in the same sentence as SMAP1 in open-access papers:
SMAP1 is named in the same sentence as 14 diseases in open-access papers, as found by Europe PMC text mining. Sharing a sentence is not in itself a finding about the gene and the disease. The quoted sentences say what the papers report.
colorectal cancer (2 papers, 2016 to 2023). A primary or metastatic malignant neoplasm that affects the colon or rectum. "The gene encoding SMAP1 is frequently disrupted in microsatellite instable colorectal cancer specimen and cell lines." (PMID 36494580, 2023). "In a parallel approach, we tested another SMAP1-deficient colorectal cancer cell line, SW48 and observed indeed a similar behavior as with HCT116 cells: Deletion of Pals1 further reduced the cortical TJ marker ZO1 and displaced PATJ and Crb3a from the junctions." (PMID 36494580, 2023). "SMAP1 is frequently mutated in microsatellite instable colorectal cancer specimen and cell lines." (PMID 36494580, 2023). "Moreover, inhibition of Arf6 reduces cell migration of Pals1/SMAP1-double deficient cancer cells and might be considered as a future therapeutic approach for a subset of colorectal cancer patients." (PMID 36494580, 2023). "Taken together, we concluded from these experiments that Pals1 functions in redundancy with SMAP1 to control the levels of active Arf6 and thus Rac1-mediated cell migration in colorectal cancer cells." (PMID 36494580, 2023). "Taken together, we identified a redundancy between SMAP1 and Pals1 in the regulation of activation of Arf6/Rac1, thereby controlling cell migration, invasion, and metastasis of colorectal cancer cells." (PMID 36494580, 2023). "SMAP1 is frequently deleted in microsatellite instable colorectal cancer specimen and cell lines." (PMID 36494580, 2023). "Finally, evaluation of mRNA expression of colorectal cancer specimen (TCGA project) revealed a poorer survival prognosis of patients suffering from colorectal cancer if tumor samples display low Pals1 and SMAP1 expression in contrast to tumors with either Pals1 or SMAP1 downregulation." (PMID 36494580, 2023). "Notably, deletion of Pals1 in three other colorectal cancer cell lines (Caco-2, DLD1 and RKO) alone does not increase cell migration or Arf6/Rac1 activity, due to the expression of the Arf6-specific GAP SMAP1." (PMID 36494580, 2023).
bleeding disorder (1 paper, 2021). "Therefore, our results predict that SMAP1 dysfunction would cause bleeding disorder, but physiologically, the effects could be opposite." (PMID 34369554, 2021).
colon adenocarcinoma (1 paper, 2018). "Kit dependencies can bias comparisons between tumor histologies, and likely explain a prior report that CCDC168 and SMAP1 are sites of microsatellite instability in colon adenocarcinoma but not stomach adenocarcinoma." (PMID 30281678, 2018).
Myelodysplasia (1 paper, 2023). Clonal hematopoietic stem cell disorders characterized by dysplasia (ineffective production) in one or more hematopoietic cell lineages, leading to anemia and cytopenia. "Interestingly, ubiquitous deletion of SMAP1 in mice alters vesicle trafficking in erythroid-myeloid progenitor cells, resulting in myelodysplasia." (PMID 36494580, 2023).
tumor (6 papers, 2016 to 2023). "Finally, we checked whether the proposed mechanism of Pals1 controlling tumor cell migration/metastasis in redundancy with SMAP1 is also reflected in patient cohorts." (PMID 36494580, 2023). "Among low-frequency MSI events, SMAP1, CCDC168 and SPINK5 harbour frameshift mutations in COAD and UCEC but not in STAD tumours." (PMID 28585546, 2017). "We found that down regulation of each of 4 genes, i.e., SMAP1 (6q13), ZNF292 (6q14), HMGN3 (6q14), and UBE2J1 (6q15) significantly increased cell growth over background in colony formation assays performed in duplicate (P ≤ 0.0139), thus supporting a tumor suppressive role for these four genes." (PMID 29312579, 2017).
cancer (5 papers, 2017 to 2023). A tumor composed of atypical neoplastic, often pleomorphic cells that invade other tissues. "Some of these genes have shown strong predictive power for MSI-H status (for example, ACVR2A and KIAA2018 for COAD, STAD and UCEC), whereas others display low recurrence for single cancer types (for example, SMAP1 for STAD)." (PMID 28585546, 2017). "ARF6 (GAPs), such as SMAP1, AMAP1 and GIT1, are also linked to cancer progression." (PMID 35143561, 2022).
SMAP1 also shares sentences with these, for which no sentence is quoted: venous thromboembolism (2 papers); acute myeloid leukemia (1); aplastic anemia (1); colon cancer (1); gastric cancer (1); prostate carcinoma (1); stomach adenocarcinoma (1); uterine cancer (1).